EDN1 (endothelin 1)
Diseases named in the same sentence as EDN1 in open-access papers (continued):
Sharing a sentence is not in itself a finding about the gene and the disease.
Cerebral ischemia (44 papers, 2010 to 2025). Restriction of arterial blood supply to the brain associated with insufficient oxygenation to support the metabolic requirements of the tissue. "We show evidence here from a small trial that the knockout of the P2Y6 receptor, required for microglial phagocytosis of neurons, prevents the delayed neuronal loss after transient, focal brain ischemia induced by endothelin-1 injection in mice." (PMID 35216419, 2022). "Both iNOS and endothelin-1 have been associated with astrocyte dysfunction in several neurological conditions, including brain ischemia." (PMID 33926378, 2021). "In addition to causing vasoconstriction, leading to cerebral ischemia, endothelin-1 has also been shown to regulate the expression of several proteins which in turn may generate different findings." (PMID 25867181, 2015). "Using a rat model of endothelin-1–induced focal cerebral ischemia, HDAC1 knockdown was achieved via stereotactic co-injection of HDAC1 siRNA." (PMID 41388741, 2025). "Focal cerebral ischemia in T2DM mice was established via injection of the vasoconstrictor peptide endothelin-1 (ET-1) into the hippocampus." (PMID 36615583, 2023). "Endothelin-1 (ET-1) is produced in large quantities by astrocytes and white blood cells during inflammation or cerebral ischemia and has a strong vasoconstriction function." (PMID 36582214, 2022). "Another study demonstrated increased NKCC1 activity in the perilesional cortex of rats challenged with focal cerebral ischemia induced by endothelin-1 (ET-1)." (PMID 33513812, 2021). "Cerebral ischemia/reperfusion injury induces increased EDN1 secretion, promotes vascular smooth muscle contraction, and aggravates low perfusion." (PMID 34017247, 2021). "In this study, we adopted an induced rat model with cerebral ischemia using the vessel dilator endothelin-1 to evaluate the potential of compound 5104434." (PMID 34638996, 2021). "Even though, there is cerebral ischemia in both situations, the intrinsic biological activity of endothelin-1 cannot be ignored." (PMID 25867181, 2015). "According to other studies, both angiotensin II and endothelin-1 are pro-inflammatory and these have previously been found to be increased in cerebral ischemia." (PMID 20187933, 2010). "In addition, focal cerebral ischemia can be induced by the stereotactic injection of endothelin-1 into the bilateral prefrontal cortex of the rat brain." (PMID 37324494, 2023). "To do this, we induced transient brain ischemia by injection of endothelin-1 into mouse brains, as this induces relatively mild damage and small infarcts which may be more likely to benefit from inhibition of microglial phagocytosis." (PMID 35216419, 2022). "Furthermore, it has been shown that during cerebral ischemia levels of the vasoconstrictive substances endothelin-1 (ET-1) and 5-hydroxotryptamin (5-HT) are increased in plasma and cerebrospinal fluid." (PMID 22848635, 2012). "Borneol can effectively reduce EDN1 levels and tends to increase CGRP levels, suggesting that it can dilate blood vessels and improve cerebral blood flow during cerebral ischemia." (PMID 34017247, 2021).
metabolic syndrome (44 papers, 2007 to 2025). A cluster of metabolic risk factors for CARDIOVASCULAR DISEASES and TYPE 2 DIABETES MELLITUS. "Mechanistically, dyslipidemia may impair microvascular vasodilation via oxidative modifications of low-density lipoprotein cholesterol, which may cause reduced nitric oxide availability, possibly in conjunction with increased expression of endothelin-1." (PMID 29077770, 2017). "Endothelial damage is possibly caused by impaired nitric oxide production and activity and alterations in endothelin-1 and endothelin A and B receptor expression for individuals with dyslipidemia." (PMID 36094942, 2022). "Increased plasma endothelin-1 levels have also been reported in obese subjects with metabolic syndrome." (PMID 22748184, 2012). "In patients with metabolic syndrome, ghrelin has benefits to normalize the balance between vasoconstrictor (endothelin 1) and vasodilating (NO) mediators, thus suggesting that this peptide has important peripheral actions to preserve vascular homeostasis in humans." (PMID 20700400, 2010). "Patients with MetS also have higher levels of vasoconstrictor endothelin-1 in their blood.The prevalence of microalbuminuria is higher in patients with Metabolic Syndrome (MetS)." (PMID 37614749, 2023). "The concentrations of early metabolic syndrome biomarkers [adiponectin, leptin, TNF-α, IL-1, IL-6, IL-10, endothelin-1, apolipoprotein B, and lipoprotein (a)] were measured and a cardiopulmonary exercise test (CPET) was performed." (PMID 38254811, 2024).
Hyperinsulinemia (39 papers, 2010 to 2026). An increased concentration of insulin in the blood. "Chronic hyperinsulinemia causes coronary vasoconstriction by increasing the release of endothelin-1(ET-1) and sympathetic nerve activity and by reducing endothelial response to vasodilators." (PMID 35090539, 2022). "Prolonged fructose feeding has been associated with hyperinsulinemia which can cause increased levels of other vasoactive factors such as endothelin-1, reactive oxygen species and uric acid." (PMID 34579006, 2021). "Concurrently, hyperinsulinemia increases secretion of endothelin-1 (ET-1), a potent vasoconstrictor." (PMID 41002997, 2025). "Contractile VSMCs remodeling can also be impaired/exacerbated by hyperinsulinemia-induced vascular endothelial cell dysfunction by releasing vasoactive compounds such as endothelin-1 (ET-1) and nitric oxide (NO)." (PMID 40137469, 2025). "Hyperinsulinemia stimulates endothelin 1 (ET-1) secretion in the endothelium and in turn increased ET-1 levels induce vasoconstriction which eventually leads to vascular dysfunction." (PMID 36983082, 2023). "Moreover, hyperinsulinemia increases the production and release of endothelin-1 by endothelial cells." (PMID 38025208, 2023). "However, during periods of physical inactivity and/or nutrient excess, hyperinsulinemia develops and has been related to elevated endothelin-1 (ET-1) mediated vasoconstriction." (PMID 32849302, 2020). "Thus, insulin stimulates endothelin-1 production and action through MAP-kinase-dependent pathways, while ET-1 induces IR and reactive hyperinsulinemia." (PMID 23046637, 2012).
melanoma (39 papers, 2003 to 2025). A malignant, usually aggressive tumor composed of atypical, neoplastic melanocytes. "Meanwhile, in vitro studies have shown that UVB radiation induces the secretion of endothelin 1 (ET-1) by keratinocytes, causing a reduction in E-cadherin production by influencing melanocytes and melanoma cells." (PMID 38396841, 2024). "In addition, endothelin-1 (ET-1)-dependent activation of the PI3K pathway could be directly linked to HIF1α stability under normoxic conditions in melanoma cells." (PMID 26000250, 2015). "We constructed recombinant plasmid for wild and mutant EDNRB and EDN1, respectively, and transfected the recombinant plasmid into mouse B16 melanoma cells in groups." (PMID 40002960, 2025). "We constructed plasmids for both wild and mutant Endothelin Receptor Type B, as well as Endothelin-1, and transfected them into mouse melanoma cells." (PMID 40002960, 2025). "In partial contradiction to the pro-melanogenic role of cadherin-mediated adhesion, UV irradiation enhancing ET-1 (endothelin-1) release by keratinocytes downregulates E-cadherin in melanocytes and melanoma cells." (PMID 38473275, 2024). "Endothelin-1 produced by ECs has been shown to promote melanoma cell migration and vessel-like channel formation, and, interestingly, LECs cultured in the media containing endothelin-1 also show enhanced cell migration." (PMID 37971882, 2024). "Keeping the focus on the VEGF family and VM, in melanoma, it has been observed that endothelin-1 (ET-1) increases the expression levels of VEGF-R3 together with its ligands VEGF-C and -D triggering VM signalling." (PMID 36224457, 2022). "More important, ET-1 (EDN1) supports MITFhigh melanoma cells via endothelin receptor B (EDNRB) and AXLhigh through EDNRA." (PMID 35406721, 2022). "The study showed an increased expression and secretion of endothelin-1 by melanoma cells, probably induced by a direct effect of BK on B2 receptors." (PMID 34068618, 2021). "Endothelin-1 was shown to downregulate E-cadherin expression in melanoma through activation of caspase-8, thus contributing to cancer invasion." (PMID 33430277, 2021). "They protect pigment cells from transformation into melanoma cells through direct interaction and in a paracrine manner via secretion of endothelin-1 (End-1) and α-melanocyte-stimulating hormone (α-melanocortin, αMSH)." (PMID 33430277, 2021). "Endothelin-1 (ET-1) contributes to the up-regulation of MCAM that will contribute for the melanoma progression." (PMID 32117980, 2020). "As for VEGFR-3, it has been proved in melanoma that endothelin-1 (ET-1) can enhance its expression and also the expression of its ligands VEGF-C and -D." (PMID 28320399, 2017). "In line with our previous findings that MITF is up‐regulated on treatment, we found that EDN1 as well as EDNRB expression increased in melanomas of patients (n = 22) on treatment." (PMID 28606996, 2017). "Indeed, EDNRB depletion through RNAi prevented EDN1 from protecting melanoma cells from BRAF inhibition." (PMID 28606996, 2017). "Signaling experiments have shown a significant deficiency in endothelin (EDN)-1 (10 nm)-induced phosphorylation of Raf-1, MEK, ERK, MITF, and cyclic AMP responsive element-binding protein (CREB) after 15 min from EDN1 treatment in WS extract (10 μg/mL) treated human melanoma cells in culture." (PMID 33919088, 2021). "Of note, HH044 treatment significantly reduced the expression of EDN1, PDGFB, and MMP9, which are known to facilitate melanoma disease progression and serve as druggable targets for pharmacotherapy." (PMID 40574005, 2025). "Endothelin-1 and SCF signaling have been reported to play essential roles in melanogenesis in human melanocytes and in several subtypes of melanoma." (PMID 30322121, 2018). "EDN1 signals through endothelin receptors, of which EDNRB is essential for melanocyte development (Saldana‐Caboverde & Kos, 2010), and its expression is highly enriched in melanoma cells (Fig EV4D)." (PMID 28606996, 2017).
melanoma (continued). "One potential algogen, the vasoconstrictive molecule endothelin-1 (ET-1), has been found to be released in high local concentrations in murine fibrosarcoma models of hyperalgesia, and was not seen in a non-sarcoma model (melanoma)." (PMID 18312658, 2008). "EDN1 is well known to support tumour growth and progression through acting on the microenvironment, and hence, interfering with EDNR signalling apart from targeting melanoma cell phenotypes could have the additional benefit of suppressing a favourable tumour microenvironment." (PMID 28606996, 2017).
chronic heart failure (35 papers, 2008 to 2024). "In patients with chronic heart failure and PH-LHD, elevated plasma endothelin-1 levels are associated with increased pulmonary pressure and greater risk of death." (PMID 37901601, 2023). "On the other hand, in patients with chronic heart failure, the profound upregulation of vasoconstrictor substances such as angiotensin II, endothelin-1, and norepinephrine may explain the relatively preserved compensatory vasoconstriction observed in this group in our study." (PMID 33105580, 2020). "We hypothesised that assessment of plasma C-terminal pro-endothelin-1 (CT-proET-1), a stable endothelin-1 precursor fragment, is of prognostic value in patients with chronic heart failure (CHF), beyond other prognosticators, including N-terminal pro-B-type natriuretic peptide (NT-proBNP)." (PMID 21264211, 2011).
portal hypertension (34 papers, 2007 to 2025). Increased blood pressure in the portal venous system. "In certain cases, portal hypertension due to liver sarcoidosis can also cause PH mediated by increased circulating endothelin-1 (ET-1) levels." (PMID 23094153, 2012). "Various circulatory agents including vasopressors such as angiotensin II, endothelin-1, and vasopressin and vasodilators such as nitric oxide, endocannabinoid, and substance P are implicated in cirrhosis-induced portal hypertension and splanchnic vasodilation, respectively." (PMID 39200187, 2024). "Additionally, EDN1 causes potent vasoconstriction, being implicated in energy metabolism, wound healing, liver fibrosis, and portal hypertension." (PMID 34828420, 2021). "Endothelin 1 (ET-1) is a 21 amino acid peptide, synthesized interendothelial, which causes prolonged and pronounced vasoconstriction by regulating vascular tone and is involved in the development of portal hypertension and porto-pulmonary syndromes." (PMID 25870693, 2014). "During fibrosis, reduced NO production and increased endothelin-1 expression in LSECs contribute to portal hypertension." (PMID 41235615, 2025). "Activated HSCs secrete endothelin-1 (ET-1), which is a molecule with potent vesoconstricting effect, promoting proliferation and fibrogenesis, and thus is supposed to contribute to portal hypertension." (PMID 35967364, 2022). "Endothelin-1 (ET-1) induces contraction, proliferation, and collagen synthesis of activated hepatic stellate cells and is a potent mediator of portal hypertension." (PMID 31231580, 2019). "In addition, H. pylori infection might worsen the liver functions and portal hypertension through overproduction of proinflammatory cytokines such as tumor necrosis factor-α, interleukins, nitric oxide, and endothelin-1." (PMID 30881448, 2019). "Vasoregulatory pathways responsible for IIR in portal hypertension include Nitric oxide-c-GMP system, aracrine endothelin-1 (ET-1) system, sympathetic alpha adrenergic pathway and angiotensin II (ATII) system." (PMID 37674997, 2022). "In non-alcoholic steatohepatitis (NASH), decreased nitric oxide and increased endothelin-1 (ET-1, also known as EDN1) released by sinusoidal endothelial cells (LSEC) induce hepatic stellate cell (HSC) contraction and contribute to portal hypertension (PH)." (PMID 34014280, 2021). "Because HSCs are liver-specific pericytes that play a key role linking fibrosis and portal hypertension, we demonstrated that LCN2 promotes EDN1 synthesis in HSCs during liver fibrogenesis." (PMID 32968110, 2020).
asthma (33 papers, 2007 to 2025). "As the receptor for asthma related gene EDN1, the 30G>A SNP in Ednrb is strongly associated with the degree of airway obstruction, especially in patients with factors that induce airway remodeling, such as asthma or smoking." (PMID 35600600, 2022). "The expression of EDN1, a potent spasmogen for the bronchus, is increased in asthma, and single nucleotide polymorphisms (SNPs) have been associated with susceptibility to this disease." (PMID 22235296, 2012). "Furthermore, genetic polymorphisms in the EDN1 promoter region have been linked to an increased incidence of left ventricular hypertrophy, and asthma, a known consequence of OSA in children." (PMID 24010499, 2013). "To date, three studies report significant association between EDN1 and asthma." (PMID 21699702, 2011). "As suggested by previous studies showing an association between EDN1 polymorphism and asthma or atopy, we hypothesised that molecular variations in theses genes could be a major determinant of the degree of bronchial obstruction in asthmatic patients." (PMID 17470272, 2007). "Uric acid induces the upregulation of endothelin-1 expression, and inflammatory mediators, such as endothelin-1, IL-6, and IL-8, have been shown to promote mucus secretion, airway swelling, and bronchial hyperreactivity." (PMID 40299440, 2025). "How Endothelin-1 drives A. fumigatus-induced airway structural changes and the importance of Endothelin-1 in patients with A. fumigatus sensitised asthma still needs to be addressed." (PMID 35205913, 2022). "Other growth factors contributing to airway remodeling in asthma include endothelin-1 (ET-1), epidermal growth factor (EGF), platelet-derived growth factor (PDGF), and vascular endothelial growth factor (VEGF)." (PMID 23853765, 2013). "Edn1 heterozygous knockout mice also show increased bronchial responsiveness and these result link EDN1 functionally to asthma and obstructive diseases." (PMID 21699702, 2011). "EDN1 was the second most differentially expressed asthma gene in the human data set and very consistent expression patterns were found in all murine data sets." (PMID 21699702, 2011). "As EDN1 displays physiological effects in the airways, the initial purpose of this study was to look for a possible association between FEV1 in asthma and the genetic differences in the endothelin system in asthmatic patients." (PMID 17470272, 2007). "Endothelin-1 (EDN1) has been involved in the development of airway obstruction and inflammation in asthma." (PMID 17470272, 2007). "Also, the ET-1 gene (EDN1) expression is elevated significantly in patients with different subtypes of asthma compared with healthy subjects." (PMID 36168358, 2022). "Endothelin-1 (ET-1), a potent vasoconstrictor, is involved in a pathway of tobacco-induced vascular dysfunction in smokers, and it is considered a mediator of asthma." (PMID 31485240, 2019). "A potential pathophysiological link could be endothelin-1 which is known to be elevated in hyperuricemia, but also in asthma and COPD exacerbations." (PMID 29866121, 2018). "Previously, EDN1 was found increased in the airway epithelium of patients with asthma where it may play a role in airway remodelling." (PMID 24282527, 2013). "There are several lines of evidence suggesting that EDN1 may play a role in the development of chronic airway obstruction in asthma." (PMID 17470272, 2007). "Based on these findings, it is considered that the release of endothelin-1 through interactions with other cytokines and the influence on many airway cells essential in asthma, may contribute to the exacerbation of asthmatic inflammation in the airways and bronchial hyperreactivity after exercise." (PMID 17973986, 2007). "Increased levels of endothelin-1 are also detected in the BAL fluid and serum from severe asthmatics, particularly those with steroid refractory asthma, and correlate with increased ASM area 19,20." (PMID 24117726, 2013).
asthma (continued). "Among genes identified in asthma GWAS, ROBO1, RORA, HLA-DQB1, IL2RB and PDE10A showed most consistent expression patterns and from asthma candidate genes, e.g. NOD1, EDN1, CCL5 and HLA-G were identified." (PMID 21699702, 2011). "While there was no general over-representation of asthma genes among differentially expressed genes, some asthma genes were consistently differentially expressed in multiple developing lung transcriptomes, e.g. NOD1, EDN1, CCL5, RORA and HLA-G suggesting key functional roles in lung development." (PMID 21699702, 2011). "However, differential expression of some asthma genes was consistent in both developing human and murine lung, e.g. NOD1, EDN1, CCL5, RORA and HLA-G." (PMID 21699702, 2011).